USP1 (ubiquitin specific peptidase 1)
Description:
Negative regulator of DNA damage repair which specifically deubiquitinates monoubiquitinated FANCD2. Also involved in PCNA-mediated translesion synthesis (TLS) by deubiquitinating monoubiquitinated PCNA. Has almost no deubiquitinating activity by itself and requires the interaction with WDR48 to have a high activity.
Synonyms: UBP
Tractability: Small molecule: a structure with a bound ligand is known; a high-quality ligand is known. PROTAC: UniProt records ubiquitination sites on it; ubiquitination databases record sites on it; a small molecule that binds it is known.
Target class: Cysteine protease; Cysteine protease CA clan; Protease; Enzyme; Cysteine protease C19 family
Chemical probes: ML323 (high quality)
Gene: Protein-coding gene on chromosome 1 (62,436,041 to 62,451,804, forward strand). Ensembl gene ENSG00000162607.
Subcellular location: Nucleus
Subcellular location (Human Protein Atlas): Nucleoplasm
Pathways (Reactome):
DNA Repair: Fanconi Anemia Pathway; Recognition of DNA damage by PCNA-containing replication complex
Gene Ontology:
Molecular function: cysteine-type deubiquitinase activity; peptidase activity; protein binding; cysteine-type endopeptidase activity
Biological process: monoubiquitinated protein deubiquitination; positive regulation of receptor signaling pathway via JAK-STAT; protein deubiquitination; regulation of DNA repair; response to UV; positive regulation of error-prone translesion synthesis
Cellular component: nucleoplasm; nucleus; peptidase complex
Genetic constraint (gnomAD): Loss-of-function variants: 17 observed, 69.58 expected, observed/expected ratio (o/e) 0.24, 90% interval 0.17 to 0.37. The upper end of that interval is the gene's LOEUF score, 0.37, which puts it in group 1 of 6, group 1 being the genes least tolerant of losing a copy. Missense variants: 723 observed, 875.6 expected, observed/expected ratio (o/e) 0.83, 90% interval 0.78 to 0.88. Synonymous variants: 340 observed, 300.42 expected, observed/expected ratio (o/e) 1.13, 90% interval 1.03 to 1.24.
Homologues: Orthologues: chimpanzee USP1 (99% identical), macaque USP1 (97% identical), dog USP1 (94% identical), pig USP1 (94% identical), rabbit USP1 (93% identical), rat Usp1 (89% identical), mouse Usp1 (88% identical), guinea pig USP1 (85% identical), tropical clawed frog usp1 (55% identical), zebrafish usp1 (49% identical). Paralogues in human: USP15 (16% identical), USP38 (16% identical), USP4 (15% identical), USP8 (15% identical), USP9X (15% identical), USP24 (15% identical), USP19 (15% identical), USP11 (15% identical), USP20 (15% identical), USP16 (14% identical), USP32 (14% identical), USP33 (14% identical), and 59 more.
Diseases named in the same sentence as USP1 in open-access papers:
USP1 is named in the same sentence as 85 diseases in open-access papers, as found by Europe PMC text mining. Sharing a sentence is not in itself a finding about the gene and the disease. The quoted sentences say what the papers report.
Fanconi anemia (34 papers, 2011 to 2025). Fanconi anemia (FA) is a hereditary DNA repair disorder characterized by progressive pancytopenia with bone marrow failure, variable congenital malformations and predisposition to develop hematological or solid tumors. "Dysfunction of the Fanconi anemia pathway can cause multiple abnormalities that lead to cancer, which are correlated with deregulation of USP1." (PMID 30319415, 2018). "USP1 serves as a pivotal regulator of DNA repair responses, particularly in the Fanconi anemia pathway and DNA translation." (PMID 39735674, 2025). "USP1 plays an important role in regulating DNA damage repair, mainly via Fanconi anemia pathway activation and trans-lesion DNA synthesis." (PMID 39513905, 2024). "USP1 targets FANCD2/FANCI to regulate the Fanconi anemia pathway (FA) and, together with USP7, targets translesional DNA repair (TLS)." (PMID 37892185, 2023). "To date, studies involving USP1 have been limited to the extent to which USP1 is important in promoting DNA damage repair in Fanconi anemia or regulating autophagy via ULK1 deubiqitination." (PMID 38012162, 2023). "USP1 can regulate the Fanconi anemia pathway, but this regulation requires the formation of a stable UAF1/USP1 protein complex." (PMID 36988464, 2023). "USP1 is known to play a critical role in Fanconi anemia, complementation group A by deubiquitinating mono-ubiquitinated FANCD2." (PMID 38012162, 2023). "In detail, decreasing SERPINB3 expression reduces the USP1‐mediated deubiquitination of FANCD2–FANCI in the Fanconi anemia pathway, thereby interfering with cisplatin‐induced DNA interstrand crosslinks repair and further contributing to HNSCC cell apoptosis." (PMID 36382555, 2022). "In parallel to its role in the process of TLS, USP1 participates in the Fanconi anemia pathway through monodeubiquitination of FANCD2 during DNA interstrand crosslink lesion repair." (PMID 35432321, 2022). "USP1 is the most well-defined DUB and implicated in multiple aspects of DNA damage regulation including the Fanconi anemia pathway and translation process." (PMID 35663242, 2022). "The most characterized functions of USP1 are evident in the multiple steps of the DNA damage repair pathway including the Fanconi anemia pathway and in the process of translesion synthesis." (PMID 33114077, 2020). "Accurate deubiquitination of the FANCD2 protein by the USP1/UAF1 complex is essential for an intact Fanconi Anemia pathway and proper DNA damage repair." (PMID 31382494, 2019). "UAF1 activates USP1, and USP1 regulates the Fanconi Anemia repair pathway by deubiquitinating FANCD2, one of the most important players in this pathway." (PMID 31382494, 2019). "USP1 is a key protein involved in several significant steps in the process of DNA damage response, including regulating the Fanconi anemia pathway, the process of translesion synthesis, and the process of differentiation in specific cellular contexts." (PMID 30319415, 2018). "USP1 regulates the mono-ubiquitination of FAND2 in the Fanconi anemia (FA) pathway, and it requires UAF1 to have deubiquitinating activity for regulation of Ub-FANCD2 deubiquitination." (PMID 26919101, 2016). "Although originally described as an endosomal protein, WDR48 has subsequently been isolated from other cellular compartments, including as a chaperone for USP1 in the nucleus as a component of the Fanconi anemia DNA repair pathway." (PMID 25855980, 2015). "USP1 is a deubiquitinase that may be functionally linked to ALT through its role in DNA replication and repair involving the regulation of Fanconi Anemia proteins and PCNA19,20." (PMID 41436729, 2025). "Notably, upregulation of USP1, RMI2, and FANCE in the 2x load group, associated with the Fanconi anemia pathway, was observed among DNA repair‐related genes." (PMID 40080399, 2025). "USP1 is a key regulator of the Fanconi anemia pathway which repairs DNA interstrand crosslinks." (PMID 38323120, 2024).
Fanconi anemia (continued). "Currently, several proteins are deubiquitinated and stabilized by USP1, and this process facilitates cancer progression, including Fanconi anemia group D2 protein and proliferating cell nuclear antigen, which are known to be involved in the DNA damage response pathway." (PMID 39513905, 2024). "The DUB proteins USP1, OTUB1, UCHL5, USP7, and PSMD14 were reported to contribute to double-strand break repair, USP1 to Fanconi anemia pathway, USP1 and USP7 to translesion repair, USP7 and USP47 to base excision repair, and USP7 and USP45 to nucleotide excision repair." (PMID 37892185, 2023). "The knockout of Usp1 in mice results in genomic instability and a Fanconi anemia phenotype." (PMID 33114077, 2020). "For example, pyridostatin acts synergistically with NU7441, an inhibitor of the DNA-PK kinase that is crucial for nonhomologous end-joining repair of DNA DSBs, and with an inhibitor of USP1, which deubiquitinates a protein in the Fanconi anemia DNA repair pathway." (PMID 31546714, 2019). "The USP1/UAF1 complex is required for regulation of the Fanconi anaemia (FA) DNA repair pathway." (PMID 29386062, 2018). "USP1 plays an important role in DNA damage response (DDR) by deubiquitinating proliferating cell nuclear antigen and Fanconi anemia group D2 protein." (PMID 39814232, 2025). "USP1 also plays a critical role in DNA repair by deubiquitinating key proteins such as FANCD2 and PCNA, thereby regulating the Fanconi anemia pathway and homologous recombination." (PMID 40940964, 2025). "Well-characterized substrates of USP1 include FANCD2 and FANCI, key components of the Fanconi anemia DNA repair pathway, as well as PCNA, which plays a central role in DNA replication and repair." (PMID 40940964, 2025). "USP1 deubiquitinates mono-ubiquitinated FANCD2/I, thereby reversing the critical step in the activation of the Fanconi anemia pathway." (PMID 38323120, 2024). "The screen also identified the deubiquitinating enzyme USP1 (ubiquitin-specific protease 1) which deubiquitinates FANCD2, a protein involved in the Fanconi anemia DNA repair pathway." (PMID 25593194, 2015). "As a DUB, USP1 regulates several factors of DDR, especially proliferating cell nuclear antigen and Fanconi anemia group D2 protein, which plays an important role in translesion synthesis and Fanconi anemia pathway." (PMID 39814232, 2025). "Finally, USP1 deubiquitinates and inactivates two components of DNA repair mechanisms: FANCD2 (a component of the Fanconi Anemia pathway) and PCNA." (PMID 21283576, 2011). "Ubiquitin specific peptidase 1, shorted as USP1, is a kind of enzyme to remove ubiquitin from proteins (DUB), which admittedly participated in regulating some pathways of damaged DNA repair, such as the Fanconi anemia (FA) pathway and translesion synthesis (TLS) process." (PMID 41328326, 2025).
osteosarcoma (32 papers, 2012 to 2026). A usually aggressive malignant bone-forming mesenchymal neoplasm, predominantly affecting adolescents and young adults. "Elevated levels of USP1 expression in osteosarcoma (OS) are closely associated with maintaining the mesenchymal stem cell state." (PMID 39062505, 2024). "USP1 expression is upregulated in several cancers and its dysregulation has been linked to cisplatin-resistance both in non-small cell lung cancer and osteosarcoma cells." (PMID 28881649, 2017). "Mounting evidence showed that USP1 facilitates cancer progression in numerous cancer types, such as osteosarcoma, gastric cancer and prostate cancer." (PMID 39814232, 2025). "miR-192-5p inhibits the proliferation, invasion, migration, and apoptosis of osteosarcoma cells by negatively regulating the expression of USP1." (PMID 39062505, 2024). "In summary, USP1 plays an oncogenic role in osteosarcoma and represents a potential target molecule for osteosarcoma treatment." (PMID 39062505, 2024). "Knockdown of USP1 in osteosarcoma cells downregulates the expression levels of ID proteins, inhibits the cell cycle, and osteogenic differentiation." (PMID 39062505, 2024). "A study revealed that USP1 is highly expressed in osteosarcoma tissues, and genetic knockout of USP1 significantly inhibits the growth and invasion capabilities of osteosarcoma cells." (PMID 39062505, 2024). "For instance, USP1 slows osteosarcoma proliferation by deubiquitinating the inhibitors of DNA binding proteins (IDs) ID1, ID2, and ID3, in order to maintain a differentiated state in low-aggressive cells." (PMID 38534381, 2024). "Studies have shown that miR-192-5p is downregulated in osteosarcoma tissues and cells, while USP1 is aberrantly overexpressed." (PMID 39062505, 2024). "USP1 expression is reportedly elevated in many tumor tissues compared to normal tissues, including osteosarcoma and breast cancer tissues." (PMID 37041150, 2023). "Ubiquitin-specific protease 1 (USP1) is a well-characterized human DUB reportedly overexpressed in and associated with maintaining the mesenchymal stem cell status of osteosarcoma (OS); however, the potential mechanisms of USP1 in OS remain poorly understood." (PMID 35637948, 2022). "USP1 deletion slowed the wound healing in osteosarcoma cells, while overexpression of TAZ merely reversed this performance in HOS cells." (PMID 35637948, 2022). "Of note, elevated expression of USP1 has been reported in several human cancers, including osteosarcoma, non-small-cell lung cancer, and breast and colorectal cancers." (PMID 35432321, 2022). "For example, the investigation of the USP1 gene on 30 osteosarcoma patients showed that 26 had similar properties resulting from the overexpression of the USP1 gene while four were different, although all patients were already diagnosed with osteosarcoma." (PMID 36293439, 2022). "Upregulation of miR-192 suppresses the progress of osteosarcoma through targeting USP1, TCF7, and XIAP." (PMID 33614788, 2021). "As a member of USP, USP1 has been indicated important in regulating cancer proliferation and metastasis, such as in osteosarcoma and lung cancer." (PMID 34873426, 2021). "Previous studies have shown that USP1 is overexpressed in multiple cancers, such as osteosarcoma, multiple myeloma, glioblastoma, and non-small-cell lung cancer (NSCLC)." (PMID 34873426, 2021). "In osteosarcoma, USP1 level was upregulated in osteosarcoma tissues and cell lines and due to the regulation of miR-192-5p." (PMID 31952546, 2020). "The knockdown of USP1 in osteosarcoma cells reduces the expression of mesenchymal stem cell markers and initiates an osteogenic development program." (PMID 33114077, 2020). "As an aspect of cancer stem cell and metastasis, a previous study, which reported that USP1 preserves osteosarcoma stem cells by deubiquitinating ID proteins also observed a relationship between USP1 and circulating tumor stem cells." (PMID 33102219, 2020).
osteosarcoma (continued). "C527 is an inhibitor of USP1 that upregulates p21 in mouse osteosarcoma cells, facilitating erythroid differentiation of leukemic cells." (PMID 33158118, 2020). "DUB inhibitors counteract the activity of DUBs associated with cancer stemness and EMT, including pimozide, which inhibits USP1 in osteosarcoma and glioblastoma." (PMID 33158118, 2020). "USP1 has also been found to play important roles in cancer cells of multiple myeloma, leukemia, osteosarcoma, glioma, and non-small cell lung cancer." (PMID 31921663, 2019). "By deubiquitinating ID proteins, USP1 contributes to prevent bHLH-mediated differentiation, and thus maintain stem-cell characteristics in osteosarcoma cells." (PMID 23937906, 2013). "The human deubiquitinase USP1 plays important roles in cancer-related processes, such as the DNA damage response, and the maintenance of the undifferentiated state of osteosarcoma cells." (PMID 22701671, 2012). "USP1 deubiquitination and stabilization of ID proteins prevents osteosarcoma cell differentiation." (PMID 41533576, 2026). "In addition, USP1 has been found to be able to inhibit the Hippo pathway in osteosarcoma cells by acting on the stability of the transcriptional coactivator with PDZ-binding motif (TAZ), further confirming its role as a tumor suppressor in osteosarcoma." (PMID 38534381, 2024). "USP1 influences osteosarcoma progression by regulating the Hippo signaling pathway." (PMID 39062505, 2024). "Moreover, previous studies have shown that USP1 was expressed at high levels in malignant diseases such as osteosarcoma, human breast cancer and hepatocellular carcinoma." (PMID 36859264, 2023). "Besides, the mechanisms by which USP1 regulates osteosarcoma cell invasion is also what need to be addressed in the future." (PMID 35637948, 2022). "Besides, wound-healing assays revealed that USP1-deletion slowed the migration of osteosarcoma cells, while overexpression of TAZ merely reversed this performance in HOS cells." (PMID 35637948, 2022). "As a deubiquitinase, USP1 has been shown to stabilize ID proteins in osteosarcoma cells." (PMID 34873426, 2021). "On the other hand, the recent finding that USP1 contributes to block differentiation in osteosarcoma raises the possibility that USP1 inhibition could be explored as a strategy for differentiation therapy in this tumor type." (PMID 23937906, 2013). "Interestingly, a more focused study of USP1 expression in osteosarcoma samples demonstrated aberrantly high levels of both USP1 mRNA and protein, which correlated with increased expression of its substrate ID2." (PMID 23937906, 2013). "Therefore, miR-192-5p may serve as a valuable biomarker, and the miR-192-5p/USP1 axis could be a new therapeutic target for osteosarcoma treatment." (PMID 39062505, 2024). "In addition, USP1 was reported to be a direct target of miR-192-5p in osteosarcoma cells." (PMID 36859264, 2023). "It has been demonstrated that ubiquitin-specific peptidase 1 (USP1) is abnormally overexpressed in breast cancer, ovarian cancer, glioma, and osteosarcoma." (PMID 39814232, 2025). "A chemical inhibitor of USP1, ML323, has been developed that showed promise in inducing cytotoxicity in cisplatin-treated non-small lung cancers and osteosarcoma cells." (PMID 35365626, 2022). "ML323 is an inhibitor of USP1 that exhibits cisplatin cytotoxicity in non-small-cell lung carcinoma (NSCLC) and osteosarcoma cells." (PMID 33158118, 2020). "USP1 deubiquitinates and stabilizes ID1, ID2 and ID3, resulting in the accumulation of ID proteins in osteosarcoma." (PMID 33114077, 2020).
osteosarcoma (continued). "It has been shown that ML323 was a more specific USP1 inhibitor than the previously reported inhibitors pimozide and GW7647, and it enhanced cisplatin cytotoxicity in osteosarcoma cells and non-small lung cancer cells." (PMID 31921663, 2019). "USP1 is known to stabilize ID1 proteins, thereby preserving stem-cell traits in osteosarcoma and glioblastoma." (PMID 30918246, 2019). "Recently, studies into USP1 inhibition have shown high efficacy in lung cancers including reversing cisplatin resistance, GBM, leukaemia and osteosarcoma." (PMID 29861848, 2018). "Consistent with our findings, USP1 levels are increased in osteosarcoma, colorectal cancer, non-small cell lung cancer, and gastric cancer." (PMID 39735674, 2025). "Given the regulatory effects of USP1 in U2OS cell lines, further explore the role of ML323 in osteosarcoma may address the current therapeutic limitations and reveal new strategies for the clinical treatment of OS." (PMID 35637948, 2022). "Overexpression of USP1 is commonly observed in osteosarcoma and colorectal, non-small cell lung, and gastric cancers, and the blockade of USP1 causes apoptosis in many cancers." (PMID 36153316, 2022). "USP1 deubiquitinates and stabilizes ID1, ID2, and ID3 proteins in osteosarcoma." (PMID 33158118, 2020). "The silencing or inhibition of USP1 expression inhibits cell proliferation in osteosarcoma, prostate cancer, and ovarian cancer, but USP1 does not affect the proliferation of tumor cells in liver, gastric, or breast cancers, indicating that its role differs in various tumors." (PMID 39513905, 2024). "Some new substrates of USP1 have also been found in several tumors, such as karyopherin subunit alpha 2 and ERa in breast cancer, ID2 in gastric cancer, c-kit and TBLR1 in liver cancer, TAZ in osteosarcoma and hepatocellular carcinoma, Snail in ovarian cancer, and PARP1 in cholangiocarcinoma." (PMID 39513905, 2024). "Furthermore, catalytically active USP1-mediated ULK1 stabilization contributes to the regulation of autophagy in cancer, and canonical autophagic flux is impaired in USP1-depleted cells through degradation of ULK1, followed by the inhibition of osteosarcoma cell growth." (PMID 36153316, 2022).